IL33 (interleukin 33)
Diseases named in the same sentence as IL33 in open-access papers (continued):
Sharing a sentence is not in itself a finding about the gene and the disease.
Stroke (continued). "Current studies widely recognize that IL-33 is an important immune regulator, which plays a protective role in intracerebral brain hemorrhage, stroke, AD, and other CNS diseases, and can alleviate disease-induced neurobehavioral deficits." (PMID 37024941, 2023). "IL-33 has been shown to be neuroprotective in models of stroke and brain infection, regulate microglial phagocytosis, reduce amyloid plaques, and increase excitatory synaptic transmission." (PMID 37415149, 2023). "Collectively, we concluded that GTA improved BBB repair and functional recovery after cerebral ischemia through lipogenesis-mediated IL-33 expression in reactive astrocytes, which suggests multiple translational potentials for stroke recovery." (PMID 37968698, 2023). "IL 1β and IL-18 were increased in stroke (p<0.001 stroke vs. steady state), while IL-33 was decreased (p<0.05 stroke vs. steady state)." (PMID 36969226, 2023). "Our previous studies in stroke model show an effect of IL-33/ST2 signaling in promoting an anti-inflammatory microglia phenotype." (PMID 35432343, 2022). "Our previous study shows that IL-33 is released from oligodendrocytes and astrocytes early after stroke, and the activation of IL-33 receptor, ST2, protects against acute ischemic neuronal and oligodendrocyte loss." (PMID 35432343, 2022). "Astrocytes increase IL-33 and CCL1 levels in response to stroke, and IL-33 is thought to promote the proliferation of Treg cells after stroke." (PMID 35743941, 2022). "Stroke also increased the concentration of IL‐33 in the BALF, however, this was unaffected by IgM‐IVIg treatment." (PMID 35881080, 2022). "We found, consistent with a previous report in stroke, that IL-33 signals on a radio-resistant responder during brain T. gondii infection." (PMID 33108405, 2020). "Exogenous IL-33 administration decreases stroke-induced CNS damage and ameliorates neurological deficits via increasing anti-inflammatory responses systemically and M2-type macrophages and microglia in the CNS." (PMID 32859229, 2020). "A role for IL-33 in stroke, neurodegeneration, EAE, and CNS infection has been described, but mechanistic understanding of IL-33 signaling during brain disease is limited." (PMID 33108405, 2020). "In a mouse model of stroke, the expression of IL-33 by oligodendrocytes and astrocytes is rapidly increased together with an upregulation of ST2 on microglia after inducing ischemic brain injury." (PMID 30515150, 2018). "Increased ischemic lesion size and long term behavioral deficits are observed in ST2 deficient mice in comparison to the wild type controls indicating a possible protective role of IL-33 in stroke." (PMID 30515150, 2018). "In an animal model of stroke, the IL-33/ST2 axis functioned as an immuno-regulatory mechanism that enhanced M2 polarization of microglia and reduced stroke." (PMID 29728120, 2018). "An association between IL-33/ST2 signaling pathway and CNS ischaemic injury has been highlighted by the findings of elevated level of sST2 in the plasma of stroke patients and its correlation with a worsened clinical outcome." (PMID 30515150, 2018). "We also confirmed that the level of serum IL-33 was an independent prognostic marker of functional outcome in AIS patients 3 months after stroke onset." (PMID 27699084, 2016). "The data showed that the anti-TLR2 antibody is able to decrease the expression of IL-17, IL-6 and IL-33, and IL-17 and IL-33 are highly increased in stroke patients." (PMID 27040385, 2016). "Serum IL-33 was higher (P < 0.05) in the stroke patients with small cerebral infarction volume compared to AIS patients with large cerebral infarction." (PMID 27699084, 2016). "Serum IL-33 level in the mild stroke groups was significantly higher than the control group (P < 0.001)." (PMID 27699084, 2016). "We found that the level of serum IL-33 was significantly higher (P = 0.001) in the mild stroke patients, compared to the severe stroke patients." (PMID 27699084, 2016).
Stroke (continued). "Further research is needed to determine whether IL-33 supplementation could benefit patients with low serum levels, thereby potentially improving stroke outcomes." (PMID 39650246, 2024). "Furthermore, the prognostic accuracy of IL-33 in stroke patients surpasses that of other commonly measured laboratory parameters and clinical measures." (PMID 39650246, 2024). "Moreover, a concentration of IL-33 ≤ 71.85 ng/L was independently predictive of post-stroke depression, as shown by a multivariate logistic regression analysis (95% CI, 1.129–7.515, P = 0.027)." (PMID 39650246, 2024). "Findings from studies in mice suggest that IL-33 is protective in models of stroke and CNS injury." (PMID 37429945, 2023). "Based on this neuroprotection from activated IL-33 receptors expressed by microglia, agents that can promote the expression and rapid release of IL-33 by astrocytes may be promising for the prevention and treatment of stroke." (PMID 37464832, 2023). "IL-33 can be released by necrotic cells following tissue damage as an endogenous danger signal or “alarmin”, binding to the ST2 protein (the only well-documented receptor for IL-33) to play a complex immunomodulatory role in rodent models of neurological diseases, such as AD, MS, and stroke." (PMID 37024941, 2023). "IL-33 promotes homeostatic synaptic plasticity, reduces amyloid plaque deposition, increases microglial phagocytosis of amyloid, improves amyloid-induced behavioral deficits, and is neuroprotective in stroke models." (PMID 37415149, 2023). "Microglia/macrophages have been identified as the main cellular targets of IL-33 in stroke models." (PMID 35432343, 2022). "For example, IL-33 treatment induces Th2-type responses and reduces post-stroke inflammation." (PMID 35432343, 2022). "Oligodendrocytes and astrocytes are the main sources of IL-33 in stroke and TBI brains." (PMID 35432343, 2022). "More importantly, whether IL‐33 can be used to predict long‐term outcomes in stroke patients warrants further clinical investigation and targeting glial cell IL‐33/ST2 signaling as treatment for stroke needs further intensive study." (PMID 32064759, 2020). "Interestingly, our result shows that IL-33 is increased along with other pro-inflammatory cytokines in serum of patients after stroke." (PMID 29540209, 2018). "Patients with higher IL-33 demonstrate a favorable outcome 3 months after the stroke." (PMID 30515150, 2018). "In addition, serum IL-33 was also significantly higher (P = 0.001) in the patients with mild stroke, compared to the patients with severe stroke." (PMID 27699084, 2016). "This is the first time to examine the relationship between serum IL-33 and stroke outcome." (PMID 27699084, 2016). "In addition, IL-33 was seen to play a key role in the recovery of stroke because we found that the expression of serum IL-33 was significantly higher in patients with favorable outcome." (PMID 27699084, 2016). "Furthermore, IL-4 released from neurons after stroke may synergistically regulate microglial responses with IL-33, providing neuroprotection." (PMID 40289984, 2025). "However, further clinical research is necessary to determine whether IL-33 supplementation could improve stroke prognosis." (PMID 39650246, 2024). "However, within our sample Il33 was not upregulated in mature stroke associated oligodendrocyte and IL33 upregulation in proliferating OPCs in situ was restricted to filament-induced MCAO infarctions in rats, but not observed after thromboembolic MCAO in mice." (PMID 39043661, 2024). "Although microglia, Treg or other cells may conduct the reparative effect, the consistent and potent role of IL-33 in repairing injured brain after stroke is more important, which may have a great translational potential if the peripheral side effects could be avoided." (PMID 37968698, 2023). "Lower levels of IL-10 and IL-33 may also be used to predict post stroke depression." (PMID 35173738, 2022).
Stroke (continued). "Additionally, human stroke patients have increased plasma levels of sST2, an inhibitory IL-33 receptor; while in mice, treatment with IL-33, a cytokine known to induce a shift toward M2 polarization, increased peripheral levels of IL-4 in the spleen and peri-infarct area." (PMID 34944064, 2021). "Therefore, IL-33 may be considered a candidate for treating human stroke via modulating the peripheral immune system after stroke." (PMID 34975893, 2021). "Furthermore, interleukin 33 was found to be neuroprotective in experimental stroke models, and the administration of interleukin 33 could reduce cognitive decline." (PMID 34030636, 2021). "The elevation of IL-33 in lesioned brains has been observed in different CNS injuries including TBI, stroke, spinal cord injury, and multiple sclerosis." (PMID 35432343, 2022). "In stroke, other Treg-modulating therapies, including CD28 superagonist, IL-33, IL-2/IL-2-antibody complex, and adoptive Treg cell transfer, have been shown to increase peripheral Treg frequencies by two- to three-fold in young mice." (PMID 33516262, 2021). "IL-33 levels were lower in HF and CAD patients vs controls, however levels were higher in stroke patients compared controls [Meta-SMD 1.455, 95% CI 0.372–2.537; p = 0.008, I2 = 97.645]." (PMID 34723980, 2021). "Meta-SMDs showed that IL-33 levels are lower in HF and CAD patients compared to controls, while the reverse was observed in stroke patients." (PMID 34723980, 2021). "Flow cytometry analyses have also confirmed high expression levels of the receptor of IL‐33 (ST2) on microglia and that the expression level dramatically increases after stroke." (PMID 32064759, 2020). "There is also increased expression of IL-33 in astrocytes during stroke rehabilitation, and IL-33 and ST2 serve as immune regulatory brakes on the process of stroke rehabilitation." (PMID 31031649, 2019). "The serum level of IL-33 was measured with ELISA and the severity of AIS patients on admission was evaluated based on the National Institutes of Health Stroke Scale (NIHSS) score." (PMID 27699084, 2016). "Many studies have reported that IL-33 could support Th2 cells, reduce macrophage foam cell formation and, probably, modulate endothelial cell function, which may play important roles in the series of events involve in the pathogenesis and development of stroke." (PMID 24107076, 2013). "Fifth, since this study focuses primarily on stroke patients, I did not analyze IL-33 concentrations in a healthy population." (PMID 39650246, 2024). "Third, although IL-33/ST2 signaling plays a dual role in various central nervous system and cardiovascular diseases, this study did not measure ST2 levels, which limits our ability to fully assess the role of IL-33/ST2 signaling in stroke prognosis." (PMID 39650246, 2024). "Similarly, the receptor of IL-33 (ST2) was highly expressed in microglia (according to flow cytometry analyses) and increased rapidly after stroke." (PMID 37464832, 2023). "Neuroprotective effects of IL-33 have been demonstrated in AD, MS, chronic pain, ICH and stroke." (PMID 36362246, 2022). "Astrocytes increase the level of IL-33 and CCL1 in response to stroke." (PMID 32174916, 2020). "However, without statistical significance, a lower concentration of IL33 was noticed on day 3 (100.4 ± 1.6 pg/mL) compared to the mean concentration in the blood serum before the stroke (763.4 ± 168 pg/mL)." (PMID 40332314, 2025). "Finally, exogenous IL-33 improved BBB repair and long-term functional recovery after stroke." (PMID 37968698, 2023).
pancreatic cancer (44 papers, 2017 to 2025). "Tropisetron-mediated IL-33 suppression provides a novel strategy to prevent and treat pancreatic cancer and perhaps other cancers associated with chronic inflammation." (PMID 40647388, 2025). "Japanese researcher Minaga K. identified a strong association between serum IFN-α, IL-33, and IgG4 concentrations, suggesting their potential utility as novel biomarkers for distinguishing IgG4-RD and autoimmune pancreatitis from pancreatic cancer." (PMID 40598658, 2025). "By inhibiting Il33 expression, pitavastatin blocks the cytokine and nuclear functions of IL-33 in chronic inflammation, effectively reducing the risk of chronic pancreatitis and pancreatic cancer in mice and humans." (PMID 38816352, 2024). "This is consistent with the observation in a pancreatic cancer mouse model, that IL33 activated tumor–associated ILC2s mediated anti-tumor immunity." (PMID 32719677, 2020). "The increased secretion of IL33 in tumor-associated fibroblasts has been reported to enhance the immunosuppressive function of ILC2s, Tregs and myeloid cells and promote the growth of pancreatic cancer." (PMID 41214328, 2025). "Notably, a recent study demonstrated that extracellular vesicles (EVs) derived from BAG6-deficient pancreatic cancer cells activate mast cells via the IL33/IL1RL1 pathway." (PMID 39814702, 2025). "Additionally, KRAS mutations in pancreatic cancer induce fibroblast autocrine signaling, elevating cytokine interleukin-33 (IL-33) secretion within the stroma." (PMID 39770538, 2024). "Other research has shown the tumor-promoting role of IL-33 by activating type 2 immune response in pancreatic cancer." (PMID 40647388, 2025). "In a recent study of pancreatic cancer, IL-33 has been reported to activate ILC2s that further induce tertiary lymphoid structures (lymphoid aggregates that in chronically inflamed tissues, including cancer, infection and inflammation)." (PMID 41520521, 2025). "Our study demonstrates that tropisetron exerts a cancer-preventive effect against pancreatic cancer by reducing IL-33 expression in pancreatitis." (PMID 40647388, 2025). "Studies have shown that fungus-derived components in pancreatic cancer can induce cancer cells to secrete IL-33 via the dectin-1-mediated Src-Syk-CARD9 pathway." (PMID 39814702, 2025). "Tropisetron effectively inhibits IL-33 expression by blocking the phosphorylation of IRF3, which helps reduce the risk of chronic pancreatitis and pancreatic cancer in mice with potential implications for humans." (PMID 40647388, 2025). "Tropisetron treatment reduced the severity of chronic pancreatitis and pancreatic cancer progression by blocking IL-33 expression." (PMID 40647388, 2025). "Given the rarity of cutaneous metastasis in pancreatic cancer, further research is required to investigate how IL‐33 affects malignant growth in organs frequently involved in pancreatic cancer metastasis." (PMID 40751595, 2025). "For example, in pancreatic cancer, fungi or fungal products can stimulate the secretion of interleukin-33 (IL-33) from PDAC cells, leading to a type II immune response that supports tumor growth by creating an immunosuppressive environment." (PMID 41249582, 2025). "Although IL-33 mediates the pancreatic cancer-preventive effect of tropisetron in our studies, future studies are essential to elucidate the role of tropisetron in modulating the broader immune response and tumor microenvironment." (PMID 40647388, 2025). "IL-33 can also stimulate the production of pro-inflammatory cytokine IL-8, potentially contributing to inflammation-related pancreatic cancer." (PMID 41272907, 2025). "IL-33-activated M2 TAMs in pancreatic cancers led to high production of CXCL3 and conferred fibroblast-to-myofibroblast transformation via CXCL3-CXCR2 signalling." (PMID 38303024, 2024). "In pancreatic cancer, IL-33 has been further elucidated as an effector molecule that induces early tumor initiation and tumor transformation [22." (PMID 38430390, 2024).
pancreatic cancer (continued). "ILC2s are another major mediator in pancreatic cancer with a dual nature predominantly dependent on its activator, IL-33." (PMID 39309440, 2024). "Recently, Ablam and his team discovered that the fungal mycobiome species Alternaria alternata is capable of triggering the secretion of IL-33 and the activation of type 2 immunity in pancreatic cancer." (PMID 39483119, 2024). "In response to intratumoral mycobiome, IL-33 activates type 2 immune response in the tumor microenvironment and promotes pancreatic cancer development." (PMID 38816352, 2024). "Consistently, the regulation of IL‐33 on cell cycle factors also has been documented in pancreatic cancer cells." (PMID 39465143, 2024). "Such opposing functions for IL-33-activated ILC2 cells have also been reported in other cancer types such as models for pancreatic cancer." (PMID 37781372, 2023). "IL-33 was enriched in pancreatic cancer and tumor-infiltrating ILC2s were activated by IL-33 which resulted in activation of CD8+ T cells and finally a strong anti-tumor immune response." (PMID 35663967, 2022). "IL-33-activated ILC2s were previously found to augment protective tissue-specific pancreatic cancer immunity." (PMID 35658010, 2022). "In pancreatic carcinomas, IL-33 drives ILC2 activation, which promotes CD103+ dendric cell recruitment through the production of CCL-5 and, consequently, CD8+ T cell activation." (PMID 35805039, 2022). "Together, IL-33 plays complex roles in pancreatic cancer, and therefore, deserves to be further investigated for future targeting." (PMID 34023857, 2021). "Further studies using a spontaneous pancreatic cancer mouse model in which the Il33 or ST2 (IL1RL1) gene is genetically engineered are required in the future." (PMID 32340025, 2020). "Because IL-33 is reported to induce apoptosis in human pancreatic cancer MIAPaCa-2 cells, we first checked the effect of IL-33 on the growth of Panc02 cells and confirmed that IL-33 did not induce cell death in these cells." (PMID 32340025, 2020). "Nuclear expression of IL-33 was also observed in activated human and rat PSCs and in human tissues of chronic pancreatitis and pancreatic cancer." (PMID 30205617, 2018). "We propose that a Porphyromonas gingivalis/neutrophil/mast cell axis may be exist in pancreatic cancer, along with a Fungus/IL-33/mast cell axis, a Fungus/mast cell/Th2 axis, and the crosstalk axis involving IL-33, eosinophils, and mast cells." (PMID 39814702, 2025). "Targeting the IRF3 pathway and IL-33 expression with safe small molecules may provide innovative therapeutic strategies to tackle inflammation-driven pancreatic cancer." (PMID 40647388, 2025). "Moreover, intratumor fungi were one of the driving forces of IL‐33 secretion in pancreatic cancer, which recruited Th2 cells and innate lymphoid cells 2 to promote cancer progression." (PMID 37771912, 2023). "The question that whether co-targeting KRAS and IL-33 increases the probability of pancreatic cancer prevention arises and remains to be validated." (PMID 36224645, 2022). "Interestingly, in addition to pancreatic cancer initiation, accumulating evidence suggests differential effects of IL-33 on the development and progression of PDAC." (PMID 34023857, 2021). "Instead, further exploration of detailed molecular mechanisms by which IL-33 induces pancreatic cancer initiation may be favorable for defining novel targets to prevent its onset." (PMID 34023857, 2021). "Collectively, this study revealed that environmental damage, in combination with KRAS mutation, induces BRD4-dependent epigenetic reprogramming, as well as identified IL-33 as an effector of environmental damage to drive early-stage neoplasia for pancreatic cancer initiation." (PMID 34023857, 2021). "With regard to pancreatic cancer, the role of IL-33 largely remains unexplored." (PMID 32340025, 2020).